SLC35A2 (solute carrier family 35 member A2)
Diseases named in the same sentence as SLC35A2 in open-access papers (continued):
Sharing a sentence is not in itself a finding about the gene and the disease.
cancer (continued). "Therefore, unveiling the expression and regulation of SLC35A2 in cancers has a guiding significance in pharmacotherapy options in clinical practice." (PMID 37275857, 2023). "Next, we used GSCA to explore whether CNV and DNA methylation in SLC35A2 affected its expression in 33 cancers." (PMID 37275857, 2023). "This is consistent with the high expression of SLC35A2 in various cancers." (PMID 37275857, 2023). "In addition, while looking into the detailed analysis obtained from TIMER database, we noticed that it was high SLC35A2 expressions that presents in cancer cells and in the vast majority of immune cells that invaded BRCA tumors and subtypes." (PMID 34944621, 2021). "Furthermore, SLC35A2 was shown to be highly expressed in a group of cancer-related genes, including the G2M checkpoint and oxidative phosphorylation." (PMID 34944621, 2021). "However, the function of SLC35A2 across human cancers remains to be systematically assessed." (PMID 37275857, 2023). "Furthermore, we studied the link between SLC35A2 methylation levels and OS in patients with cancer." (PMID 37275857, 2023). "Therefore, it has become key to understanding this membrane protein family in cancer metabolism research, which further indicates that SLC35A2 might play an important role in cancer development and cancer metabolism." (PMID 37889544, 2023). "Therefore, DNA copy number amplification and methylation are two factors that may contribute to changes in SLC35A2 expression in cancers." (PMID 37275857, 2023). "Conversely, the CNV of SLC35A2 showed a negative association with five cancer types." (PMID 37275857, 2023). "In contrast, SLC35A2 was found to have negative correlations with cancer-associated fibroblast XCELLs, and CD8+ T cells in the HER2 subtype; natural killer (NK) cell-activated CIBERSORT-ABS in the luminal A subtype, and hematopoietic stem cells in the luminal B subtype." (PMID 34944621, 2021). "Our results identify that these cancer metabolism-related gene sets and signaling pathways are closely related to SLC35A2-regulated MYC, indicating that SLC35A2-MYC holds an important role in CRC progression." (PMID 40303483, 2025). "Subsequently, we analyzed SLC35A2 pan-cancer expression using the TIMER database and discovered that SLC35A2 was upregulated in COAD and READ." (PMID 37889544, 2023). "In most human cancers, such as STAD, STES, BLCA, PCPG, LUAD, MESO, SLC35A2 expression was found to exhibit significant positive associations with TMB, and negative correlations in COAD, LAML." (PMID 37467193, 2023). "Overall, high expression of SLC35A2 was found in 37.5% (15/40) adjacent noncancerous tissues and 56.9% (182/320) cancer tissues." (PMID 38639872, 2024). "After determining the potential prognostic value of SLC35A2 in STAD patients, we further explored the promoter methylation and genetic alterations levels of SLC35A2, to elucidate its relationship with the occurrence and development of cancer." (PMID 37467193, 2023). "To date, the comprehensively analyze SLC35A2 in pan-cancer has not yet been reported." (PMID 37275857, 2023). "However, the prognostic or predictive values of SLC35A2 on immunotherapies have not yet been reported in multiple cancer types." (PMID 37275857, 2023). "A negative relationship between SLC35A2 expression and DNA methylation was found in 26 cancers." (PMID 37275857, 2023). "To date, the roles of CCDC24 and SLC35A2 have not been analyzed in cancer-related studies." (PMID 32716908, 2020).
infection (10 papers, 2018 to 2025). The state of being infected such as from the introduction of a foreign agent such as serum, vaccine, antigenic substance or organism. "Taken together, these data indicate that SLC35A2 plays differential roles in the infection and spread of different paramyxoviruses during infection in A549 cells." (PMID 39792924, 2025). "Taken together, these data indicate that SLC35A2 plays differential roles in the infection and spread of different paramyxoviruses during infection of A549 cells." (PMID 39253522, 2024). "We then used a SeV reporter virus expressing eGFP (rSeVCeGFP) to directly assess the impact of SLC35A1 or SLC35A2 during infection." (PMID 39253522, 2024). "We observed that despite lower MuV F mRNA at late times post-infection in SLC35A2 KO cells compared to controls, the amount of infectious viral particles produced in both cell lines at 48 hpi was the same, suggesting an important role for cell-to-cell fusion in MuV spread." (PMID 39792924, 2025). "However, SLC35A2 KO cells revealed unknown critical roles for this factor in virus-cell and cell-to-cell fusion events during infection with different paramyxoviruses." (PMID 39253522, 2024). "However, we show successful infection of SLC35A2 KO and control cell lines with the same MuV virus stocks and production of similar levels of MuV infectious viral particles in SLC35A2 KO and control cells indicating normal activity of the F protein during virus entry in these conditions." (PMID 39253522, 2024). "Interestingly, infections in SLC35A2 KO cells displayed varied phenotypes across these viruses." (PMID 39253522, 2024). "The infection titer in the culture supernatants was also reduced in the SLC35A1 KO, SLC35A2 KO, or Triple KO cells." (PMID 37819933, 2023).
tumor (10 papers, 2021 to 2025). "In online database research, high SLC35A2 expression was observably associated with high tumor stage and lymph node metastasis." (PMID 37889544, 2023). "Correlations between SLC35A2 expression and DNA methylation, genetic alterations, tumor mutation burden (TMB), microsatellite instability (MSI), and tumor microenvironment were performed using Spearman’s correlation analysis." (PMID 37275857, 2023). "We also assessed the association between tumor stages and SLC35A2 expression." (PMID 37275857, 2023). "SLC35A2, on the other hand, generally exhibited higher expression in tumor tissues compared to normal tissues, including CRC." (PMID 40303483, 2025). "The immunohistochemical staining of SLC35A2 was observed in 320 tumor tissue samples and 40 paracancerous tissue samples." (PMID 38639872, 2024). "SLC35A2 plays an important role in regulating glucose metabolism, and a large number of tumor cells have high metabolic activity." (PMID 38639872, 2024). "By employing the "Correlation" module of TIMER analysis platform, we explored the correlation of SLC35A2 gene expression level with tumor infiltrating immune cell density and cell-specific markers." (PMID 37467193, 2023). "The potential role of SLC35A2 in the tumor immune microenvironment was evaluated via EPIC, CIBERSORT, MCP-counter, CIBERSORT-ABS, quanTIseq, TIMER, and xCell algorithms." (PMID 37275857, 2023). "As indicated by our result, SLC35A2 expression exhibited significantly positive associations with TMB in STAD, revealing the higher potential of patients to benefit from tumor immunotherapy in line with the higher expression of SLC35A2 in STAD." (PMID 37467193, 2023). "On the one hand, the expression level of SLC35A2 exhibited a weak positive correlation with the infiltration level of CD4+T cells, and the correlation suggested the role of SLC35A2 in the regulation of STAD tumor immunology." (PMID 37467193, 2023). "There was a significant correlation between the expression of SLC35A2 and pathological stage of the tumor (p < 0.05)." (PMID 37889544, 2023). "No statistical significance was revealed on the protein expression of SLC35A2 in STAD between primary tumor tissue and normal tissue." (PMID 37467193, 2023). "In summary, our research showed that the expression of SLC35A2 is related to tumor stage and lymph node metastasis." (PMID 37889544, 2023). "Furthermore, our CRC cell models revealed the tumor-promoting role of SLC35A2 and discovered that the upregulation of SLC35A2 is associated with chemoresistance against irinotecan." (PMID 40303483, 2025). "Additionally, SLC43A2 and SLC35A2 are positively correlated according to TCGA database, hence the relationship between SLC35A2 and tumor immunity is worth exploring." (PMID 38639872, 2024). "SLC35A2 may further affect tumor immunity mainly by regulating CD8+T cells, NK cells, B cells, and CD4+T cells, and the effect of SLC35A2 on immunity varies across tumor types." (PMID 37275857, 2023). "Relationship between SLC35A2 levels and 28 tumor immunoinfiltrating cell subtypes using TISIDB." (PMID 37467193, 2023). "In addition, SLC35A2 is strongly amplified after treatment with the DNA damage agent cisplatin, and plays a major role in the sensitivity of cisplatin in tumor therapy." (PMID 37889544, 2023). "Despite the systematically analysis of SLC35A2 in this study, there still exist the following shortcomings: Firstly, in vivo and in vitro validation should be carried out to determine the clinical validity of SLC35A2 in patient prognosis and the mechanism of promoting tumor." (PMID 37467193, 2023). "We identified a substantial link between SLC35A2 and an increase in tumor stage in BRCA patients." (PMID 34944621, 2021).
tumor (continued). "The high expression of SLC35A2 in many tumors shows that SLC35A2 may be a tumor-related gene." (PMID 37889544, 2023). "Increased SLC35A2 expression may be correlated with immunodepression in the tumor microenvironment." (PMID 37275857, 2023). "Solute carrier family 35 member A2 (SLC35A2), which belongs to the SLC35 solute carrier family of human nucleoside sugar transporters, has shown regulatory roles in various tumors and neoplasms." (PMID 37275857, 2023). "We further assessed the differences in SLC35A2 expression using the UALCAN database, as well as the promoter methylation, and protein levels between STAD primary tumor and normal tissues." (PMID 37467193, 2023). "SLC35A2 expression in CRC tissues was significantly higher than that in adjacent normal tissues (p < 0.001), and SLC35A2 was found to be higher in tumor pathological stages III and IV than in stage I and stage II (p < 0.05)." (PMID 37889544, 2023). "In the present report, the close relationship between SLC35A2 and immune cells (especially macrophages and CD4+T lymphocytes) was also revealed in the tumor microenvironment." (PMID 37467193, 2023). "Overexpressed levels of the SLC35A2 and SLC35A4 proteins was discovered in tumor tissues in a way similarly to patterns reported in BRCA patient samples of the HPA dataset." (PMID 34944621, 2021). "The current study observed that SLC35A2 exhibits higher expression in CRC tumor tissues than in normal tissues." (PMID 40303483, 2025). "Thus, the function of SLC35A2 is closely related to the infiltration of CD4+T cells and macrophages in the tumor microenvironment, which is expected to serve as a potential immune-related marker in STAD tumors." (PMID 37467193, 2023). "The down-regulation of SLC35A2 was found in only two tumor tissues (KIRC, THCA), while no change was revealed in the expression of other tumors (KICH, KIRP and so on)." (PMID 37467193, 2023). "Normal breast, liver, and cortical tissues were negative for SLC35A2 IHC staining, whereas tumor tissues were intensely stained." (PMID 37275857, 2023). "Meanwhile, SLC35A2 was also correlated with “DNA damage Double-strand break repair via homologous recombination”, and “Transcription-Negative regulation of HIF1A function”, which are considered as BRCA-related immunological and cell-cycle pathways that are crucial to tumor development." (PMID 34944621, 2021).
genetic disease (2 papers, 2021 to 2022). "In terms of treatability, TSC1-, TSC2-, SLC35A2-, ATP7A-, ALDH7A1-, and MMACHC-related disorders had specific therapeutic regimens and accounted for 18.5% (19/103) of the cases with genetic disorders." (PMID 35330882, 2022).
neurological disorders (2 papers, 2019 to 2025). "Pathogenic variants in SLC35A2, whether germline or somatic, have been increasingly recognized as causes of a spectrum of neurological disorders." (PMID 41373710, 2025). "Therefore, lesion specific de novo somatic variants in SLC35A2 could be one of the etiologies of neurological disorders in addition to germline de novo variants." (PMID 31231989, 2019).
bacterial infection (1 paper, 2022). "Strikingly, bacterial infection of human macrophages induced a global reduction in levels of the UDP-GalNAc transporter, SLC35A2." (PMID 36015029, 2022).
neurodevelopmental disorder (1 paper, 2019). A behavioral and cognitive disorder with onset during the developmental period that involves impaired or aberrant development of intellectual, motor, or social functions. "A pathogenic SLC35A2 variant was never expected based on clinical features, suggesting that whole‐exome sequencing has great utility for differential diagnosis of congenital neurodevelopmental disorders." (PMID 31231989, 2019).
SLC35A2 also shares sentences with these, for which no sentence is quoted: colon cancer (2 papers); epileptic syndrome (2); Failure to thrive (2); Fusarium infection (2); galactosemia (2); Hyperbilirubinemia (2); lung cancer (2); Alzheimer disease (1); amyotrophic lateral sclerosis (1); Angelman syndrome (1); Arrhythmia (1); Arts syndrome (1); bladder cancer (1); brain disorder (1); breast invasive carcinoma (1); carcinoids (1); cervical squamous cell carcinoma (1); cholangiocarcinoma (1); congenital disorder of glycosylation type I (1); congenital myasthenic syndrome (1); cortical dysplasia (1); endocervical adenocarcinoma (1); Epileptic spasm (1); esophageal carcinoma (1); fatty liver disease (1); fructose intolerance (1); glioma (1); hypertensive disorder (1); hypertriglyceridemia (1); infantile epileptic encephalopathy (1).
A further 37 diseases each share a sentence with SLC35A2 in 1 paper.